BECN1 (beclin 1)
Diseases named in the same sentence as BECN1 in open-access papers (continued):
Sharing a sentence is not in itself a finding about the gene and the disease.
tumor (continued). "This review describes how autophagy contributes to HCC at different stages, outlines the dual functions of lncRNAs as oncogenic drivers or tumor suppressors, and illustrates their integration into key signaling networks of autophagy (e.g., PI3K/AKT/mTOR, AMPK, Beclin-1)." (PMID 40789840, 2025). "In fact, mice treated with the autophagy-inducing peptide Tat-BECN1 exhibit no signs of distress during treatment and experience reduced tumor growth." (PMID 40754831, 2025). "For instance, RT-induced AMPK activation could induce the phosphorylation of Beclin 1, which could bind to the SLC7A11 module in system xc- to block cystine import and facilitate tumor cell ferroptosis." (PMID 41041050, 2025). "Autophagy has a very complex role in cancer, and in our study, we utilized Beclin-1 to drive autophagy toward promoting tumor cell death rather than survival, thereby increasing the efficacy of our combination therapy." (PMID 40403026, 2025). "Additionally, histological analysis in the tumor xenograft tissue sections showed elevated levels of LC3, BECN1 and reduced p62 levels in the DHX9- knockdown group." (PMID 40659605, 2025). "Thus, Immunohistochemistry analysis of tumor sites revealed higher expressions of BIRC2/cIAP1 and Beclin-1 in PanNET patients compared to healthy controls." (PMID 38596136, 2024). "The exact function of Interleukin-7 (IL-7) in controlling tumor cell autophagy, lymphangiogenesis, growth, and cell death is not completely clear; studies are centered on mTOR and Beclin-1." (PMID 39650649, 2024). "Among the fourteen ferritinophagy-related genes studied, ten exhibited significant differences between tumor and normal samples: NCOA4, FTH1, FTL, SNCA (all p < 0.0001), BECN1 (p = 0.031), ELAVL1 (p = 0.00023), TNF (p = 0.00074), ATG16L1, ATG7, and ZFP36 (all p < 0.0001)." (PMID 39593730, 2024). "Furthermore, WB analysis revealed higher expression levels of CH25H, Beclin 1, LC3II/LC3I proteins, and lower expression levels of p‐AKT, PI3K, p62 proteins in the tumor+oe‐CH25H compared with the tumor+oe‐NC." (PMID 39428922, 2024). "The expression of BECN1, ATG3, and ULK1 significantly altered between normal and tumor patients." (PMID 37790849, 2023). "BECN1 could exhibit its tumor-suppressive character in CRC patients with BECN1 defect, which was supported by the evidence that activation of autophagy through overexpressing BECN1 showed a therapeutic effect and inhibited CRC growth." (PMID 37108476, 2023). "BECN1 is a regulatory subunit of the class III phosphatidylinositol 3-kinase complex I (PI3KC3–C1) needed for canonical membrane elongation; it is also related to the endocytic pathway and tumor-suppression." (PMID 37883843, 2023). "Beclin 1 could enhance the autophagy of tumor cells, and RGD could enhance the cellular uptake of melanin-like nanoparticles by tumor cells, to effectively inhibit tumors under the dual strategy of improving tumor autophagy and photothermal therapy." (PMID 36901791, 2023). "FBXW7 increased BECN1, Atg7, and LC3 levels in CAL27 xenograft tumor model." (PMID 37249289, 2023). "UVRAG regulates BECN1 expression, suggesting that the interaction between UVRAG and BECN1 may be a condition for the tumor suppressive effect." (PMID 37168865, 2023). "Furthermore, ablation of BECN1 inhibits xenograft tumor growth through elevated RB expression and reduced autophagy, while simultaneous silencing of RB1 restores tumor growth but has little effect on autophagy." (PMID 36230664, 2022). "Although the specific mechanism whereby BECN1 inhibits tumor growth is not known, there is evidence suggesting that BECN1 modulates the subcellular localization of E-cadherin, highlighting a potential crosstalk between both proteins." (PMID 35832792, 2022).
tumor (continued). "Therefore, we evaluated the expression of the main autophagy markers ATG5, Beclin 1 and LC3 in tumor tissue." (PMID 35751683, 2022). "This includes the tumor suppressor LKB1, AMPKα1, ULK1, Atg14 and Beclin-1." (PMID 36578014, 2022). "We first investigated whether BECN1, LC3, and ATG10 are essential for maintaining tumor cell proliferation under metabolic stress, similar to what has been reported for ATG7." (PMID 35681458, 2022). "Knocking down BECN1 significantly decreased the tumor promoting effects of GNIP1 no matter on cell proliferation or migration." (PMID 36042481, 2022). "Moreover, we observed the mice-bearing ASH-3 tumor which were sacrificed on day 7, 21, and 28, tumor samples also showed the identical result that decreased the expression of p62 and increased the conversion of LC3-I to LC3-II and the expression of beclin-1." (PMID 36118522, 2022). "While the expression of SUSD4 did not affect EGFR downstream signaling or Beclin-1 dissociation from Rubicon, it affected the activation of the tumor suppressor LKB1 and AMPKα1." (PMID 36578014, 2022). "Whereas, negative expression of Beclin-1, being a tumor suppressor gene, favors the development of hepatocarcinogenesis." (PMID 33906303, 2021). "In addition, QFG treatment inhibited EMT and induced autophagy progression in CRC tumor cells, including that QFG upregulated the expression of E-cadherin, beclin-1, and LC3-II, but downregulated the expression of N-cadherin, vimentin, TWIST1, and p62." (PMID 34887935, 2021). "All these suggested data might prevail the way of considering Beclin-1 altered expression as a sign of HCC development and tumor aggression." (PMID 33906303, 2021). "TLR9 overexpression increased HCC cell proliferation, whereas TLR9 inhibition from hydroxychloroquine (HCQ) decreased HCC cell proliferation, tumor growth, oxidative stress marker (SOD1), and the formation of autophagosome bodies (reduced ATG5 and Beclin-1 expression)." (PMID 34203465, 2021). "All HCC studied cases with vascular invasion and multinodular tumor revealed altered Beclin-1 expression either negative or over expression." (PMID 33906303, 2021). "The expression levels of LC3 (P = 0.015) and Beclin-1 (P = 0.024) were significantly higher in F. nucleatum-positive tumours than in F. nucleatum-negative tumours." (PMID 33299132, 2021). "In this respect, it is worth noting that no one tumor had a deep (homozygous) co-deletion of both BECN1 and BRCA1, which is consistent with the fact that complete loss of these tumor suppressor genes is incompatible with cell survival." (PMID 33670664, 2021). "Levels of autophagy-related proteins, namely LC3, Beclin-1, and p62, were immunohistochemically assessed in patient tumor and non-tumor tissues." (PMID 34273969, 2021). "In tumors progressing to late stages, autophagy can maintain cancer cell survival and growth, and one such mechanism through which this is achieved is overexpression of BECN1 rather than reduced expression, then contributing to tumor growth and survival." (PMID 34685652, 2021). "In addition, silencing mTORC1 and eIF4E upregulated Beclin-1 and LC3 and decreased the expression of HIF-1α, thereby inhibiting tumor cell proliferation." (PMID 34917504, 2021). "Both LC3B protein and Beclin 1 protein are overexpressed in tumor tissues compared with normal tissues." (PMID 34094898, 2021). "It is to be noted that no one tumor had a deep (homozygous) co-deletion of both BECN1 and BRCA1, and only one tumor had a deep deletion of BRCA1 associated with shallow deletion of BECN1." (PMID 33670664, 2021). "Indeed, inhibition of Atg5 or Beclin-1 reduce the phosphorylation of STAT3, an important transcription factor involved in tumor survival and resistance to T cell cytotoxicity." (PMID 34745965, 2021).
tumor (continued). "LC3B-II and ATF4 protein were increased in the muscle of KPC but not KPC IL6KO tumor–bearing mice, while Beclin-1 was unchanged in muscle of mice with KPC tumors and actually decreased in muscle of mice with KPC IL6KO tumors." (PMID 33851955, 2021). "Included factors were primary tumor (T) (I, II vs III, IV), N stage (N0 vs N1–3), tumor grade (well to mod vs poor), lymphatic invasion, vascular invasion, neural invasion, SKP2 expression, Beclin-1 expression, tumoral FOXP3 expression, and number of Tregs (<15/HPFs, ≥15/HPFs)." (PMID 34414959, 2021). "Consistently, we also noticed that the expression of ATG7 and BECN1 were predominantly located at the tumor edge rather than tumor nest by IHC in these tumor tissues." (PMID 34483138, 2021). "We found that knockdown of Beclin‐1 did not inhibit tumor growth, but significantly sensitized NEK2‐OE KMS11 MM cells to BTZ." (PMID 31955515, 2020). "Previously reported findings suggesting that some cancers have only BRCA1 deleted but not BECN1 deleted, fail to hold true with increased growth and precision of the database of tumor CNAs." (PMID 31923184, 2020). "We hypothesized that 6-Gingerol promotes rust disease and leads to tumor death by modulating USP14 expression and inducing Beclin 1-dependent autophagy." (PMID 33281606, 2020). "While Beclin 1 depletion alone did not have observable effects on tumour growth compared to those of shGFP in the vehicle group, treatment with birinapant and emricasan induced a 50.3% reduction in the growth of the tumour." (PMID 32457484, 2020). "The expression of autophagy-related genes light chain 3 (LC3), Beclin-1, ATG5 and p62 could be used as indicators of tumor recurrence and poor prognosis." (PMID 33004943, 2020). "Similar tumor sizes are obtained in tumors expressing BECN1‐shRNA or scramble‐shRNA developed in nontreated mice; however, tumors expressing BECN1‐shRNA in BTZ‐treated mice are significantly smaller than those expressing scramble‐shRNA." (PMID 31955515, 2020). "Indeed, disruption of this interaction using a small molecule, Tat-Beclin 1, in mice bearing BT-474-VH2 xenografts resulted in increased autophagy induction and reduced tumor progression as effectively as treatment with the tyrosine kinase inhibitor lapatinib." (PMID 33224954, 2020). "Additionally, we found BECN1, DAPK1, VAMP7 and SIRT1 genes were correlated significantly with survival status, gender, primary tumor and tumor stage (all P < 0.05)." (PMID 32998713, 2020). "Moreover, ABHD5 (abhydrolase domain containing 5) shows the tumor suppressive role in colorectal cancer and regulates the autophagy and CRC tumorigenesis via interaction with Beclin-1." (PMID 33375363, 2020). "In addition, western blot analysis of tumor tissues from mouse xenografts demonstrated an increase in LC3-II conversion and Beclin 1 expression in CPT-treated mice, whereas p62/SQSTM1 expression was decreased." (PMID 32903546, 2020). "In tumor samples from patients with colorectal cancer, the expression of the glycoprotein P (P-gp) was found to be positively correlated with the expression of the autophagy markers LC3 and beclin-1." (PMID 33233671, 2020). "Immunoblot assay showed that combination treatment clearly upregulated expressions of LC3-, Beclin-1, cleavad-caspase 7 and -PARP, and downregulated SQSTM1 expression compared to single treatment in xenograft tumor specimens, which were in consistent with the finding in vitro." (PMID 32226300, 2020). "Genes coupled with autophagy, i.e. Beclin-1 and LC3, induce autophagy and may suppress the tumour growth." (PMID 30362386, 2019). "Furthermore, similar to Beclin 1, UVRAG is also thought to have tumor suppressor activity, as it is regularly monoallelically deleted or mutated in these cancers." (PMID 30397185, 2019). "Beclin-1, ARID1A, CA9 and IDH1 were highly expressed in ICC tumor tissues." (PMID 30849962, 2019).
tumor (continued). "Moreover, there are other autophagy-promoting components of the Beclin 1/Vps34 complex, namely UVRAG and Ambra1, which are known to be tumor suppressors." (PMID 30717078, 2019). "Whereas knockdown Beclin 1 did not impact PI cytotoxicity, overexpression of Beclin 1 increased the anti-tumor effects of PIs in ATC cells." (PMID 29184971, 2018). "The autophagy process in solid tumors was validated by immunochemistry of LC3B and Beclin‐1 as well as Western blotting of Beclin‐1, in which the expression of both indicators was upregulated by TAN administration, confirming the tumor‐suppressing effect of TAN in vivo." (PMID 29316373, 2018). "These suggested that decreased Beclin-1 might have tumor suppressor function in HCC and indicated that decreased Beclin-1 expression may signify the poor prognosis of HCC." (PMID 30107804, 2018). "Moreover, this dual regulation of MCL-1 and BECLIN 1 adds another layer to the complex functions of USP9X, which can act as potential oncogen or tumor supressor." (PMID 29186924, 2017). "Finally, we detected Vps34, Beclin 1, LC3 II, p62/SQSTM1, unprenylated Rab7, prenylated Rab7, caspase 8, caspase 3 and PARP proteins in xenografted tumor samples." (PMID 28147319, 2017). "Moreover, Beclin-1 and ATG7, which act downstream of ULK1, were also significantly upregulated in tumor tissues compared with the corresponding background tissues." (PMID 28079894, 2017). "Also, haploinsufficiency of Beclin 1, which is directly phosphorylated by AMPK, increases the incidence of spontaneous tumor development in Beclin 1+/− heterozygous mutant mice." (PMID 28279189, 2017). "Daily tumor growth, in mm3 per day, was lowest in LY3023414-treated tumors with Beclin-1 shRNA." (PMID 29228741, 2017). "Tumours missing nuclear Beclin-1 immunostaining or showing a weak nuclear Beclin-1 staining were classified as negative." (PMID 27444698, 2016). "In this context, it was shown that targeting BECN1 in mesenchymal cells is sufficient to restore CTL-mediated tumor cell lysis, without affecting the mesenchymal morphology and the expression of EMT markers." (PMID 26910842, 2016). "Interestingly, tumor spheres expressed the significantly lower level of ATG5, ATG7, BECN1 and LC3B mRNAs." (PMID 27934912, 2016). "However, the combination of Beclin-1 suppression and DDP treatment significantly decreased tumor growth compared with DDP plus scrambled control shRNA, as evidenced by the tumor volume and tumor weight data (p<0.01)." (PMID 25923669, 2015). "In xenografts expressing wild-type Beclin 1, but not Beclin 1 S90A, there was a significant reduction in tumor p62 staining as compared with empty vector controls, suggesting increased levels of autophagy in the tumors." (PMID 25693418, 2015). "Similar to the results of CQ treatment, suppression of Beclin-1 expression by shRNA did not impact tumor growth." (PMID 25923669, 2015). "During oncogenesis in genetically engineered mice, reduced hemizygous expression of genes required for autophagy (BECN1, Atg4, ATG5, Atg7) can accelerate spontaneous or chemically induced tumor formation, suggesting that autophagy can serve as a tumor suppressor." (PMID 26247722, 2015). "Beclin 1, a gene in mammals similar to the Atg 6 gene in yeast, is a part of a type-III phosphatidylinositol 3-kinase complex that is necessary for autophagic vesicle formation for tumor suppression." (PMID 25730388, 2015). "Immunoblotting analysis of tumor lysates demonstrated that sorafenib treatment resulted in downregulation of PTEN, increased the activation of Akt and caspase-3, and upregulated LC3-II and Beclin-1 expression." (PMID 26311740, 2015). "Similar to Beclin 1 knockdown, we found that suppression of the ubiquitin-specific peptidase, USP10, or a small molecule inhibitor of the deubiquitinases USP10 and USP13, i.e., spautin-1, can increase radiation-induced DSBs and promote tumor cell death." (PMID 24956373, 2014).
tumor (continued). "Beclin 1, the mammalian homolog of yeast ATG6, is a potential haploinsufficient tumor suppressor gene, but such a role is not entirely evident based on data from human cancer patient samples." (PMID 25006588, 2014). "It has been demonstrated that beclin-1 knockout mice had an increased incidence of several cancers, including HCC, and a recent study showed lower expression of beclin-1 in human HCC tissues compared with the adjacent non-tumor regions." (PMID 25533006, 2014). "It was found that while tumours with a high expression of BECLIN 1 were equally distributed in I-II and III grade, tumours negative or low expressing BECLIN 1 more frequently (18 out of 20) belonged to grade III." (PMID 25136588, 2014). "While the role of Beclin 1 and UVRAG in DNA damage has been studied in the setting of tumorigenesis, little is known about the molecular details of their role in tumor cell response to cancer therapy." (PMID 24956373, 2014). "On the opposite, BCL-2 and BECLIN 1 were not detectable (by western blotting) in the tumour case 2, and in spite of this the tumour was intensely LC3 positive, which possibly was associated with BECLIN 1-independent autophagy." (PMID 25136588, 2014). "Taken together, these data indicate that Beclin 1 and UVRAG confer protection against radiation-induced DNA DSBs and may maintain centrosome stability in established tumor cells." (PMID 24956373, 2014). "Similarly, several proteins that interact with Beclin-1 and positively regulate autophagy, such as AMBRA 1, BIF-1, and UVRAG, have been shown to display antiproliferative or tumor suppressor effects." (PMID 25328887, 2014). "Further, Beclin-1 expression correlated with tumor differentiation in Bcl-xL+ but not in Bcl-xL− HCC patients." (PMID 25295245, 2014). "(E) Relative low levels of beclin-1 and LC3-II protein were found in tumor tissues." (PMID 23935917, 2013). "BECN1/NF-κBp65 gene expression was observed to be correlated with HCC tumor size (P<0.05), but not with patient age, Edmondson tumor type, hepatitis B surface antigen (HBsAg) or tumor metastasis (P>0.05)." (PMID 23833647, 2013). "The low expression of Beclin 1, Bcl-xL and Bad we demonstrated in HCC patients points to a reduced autophagy that may favor the onset and progression of tumor." (PMID 22928777, 2012). "It is possible the Beclin 1+/− had no affect in Lck-Bax38/1 mice due to the high penetrance and rapid tumor development in these mice." (PMID 21611191, 2011). "Notably, unlike Beclin-1, which is contextually activated to facilitate tumor-suppressive autophagy, ATG-4B suppression by BCc1 represents a selective inhibition of pro-survival autophagic flux." (PMID 41550506, 2026). "Moreover, the expression levels of CD86 (M1 macrophage marker) and CSF1R (M2 macrophage marker) were positively correlated with those of BECN1 (autophagy regulator) and BCL2 (only CD86) that were in turn correlated with MTOR expression in tumor B cells and in the CD86+ macrophage subtype." (PMID 41415285, 2025). "Inhibition of autophagy, either through 3-methyladenine treatment or knockdown of Beclin-1 or Atg12, significantly reduces the ability of human embryonic kidney cells (HEK293T) and malignant melanoma cells to present model antigen OVA or endogenous tumor antigens." (PMID 40248706, 2025). "Alterations in BECN1 and some ATG genes, such as ATG5 and ATG4, which limit the efficacy of autophagic processes, have also been observed in liver, breast, prostate and ovarian tumors, confirming that autophagy plays a tumor-suppressive role in different tissue contexts." (PMID 39996745, 2025).